KRAS (KRas proto-oncogene, GTPase)
Diseases named in the same sentence as KRAS in open-access papers (continued):
Sharing a sentence is not in itself a finding about the gene and the disease.
tumor (continued). "Moreover, STK11 mutations are associated with a high disease aggressiveness in patients with KRAS exon 2 p.G12D mutation, while its loss of function has been linked to tumor development and progression." (PMID 34944952, 2021). "Thus, the tumor cells with KRAS wt 4T1 cell, Pan02 cell, KRAS G12C-mutated LLC cell, and KRAS G12D-mutated CT26 cells were used." (PMID 34578339, 2021). "In the primary tumor biopsies, KRAS was found mutated in 13/38 cases (34%)." (PMID 34943432, 2021). "CMS1 (MSI) and CMS3 (high KRAS mutations) contribute to 16% of all tumor subtypes, respectively." (PMID 33570712, 2021). "Prior to the investigation of KRAS-mutated ctDNA in plasma, KRAS assessment was performed in tumor tissues of 22 patients with PDAC who underwent chemotherapy using RASKET with a sensitivity of 1–5% and droplet digital polymerase chain reaction (ddPCR) with a sensitivity of 0.01–0.1%." (PMID 34675229, 2021). "More than 65-year-old, advanced TNM stage, history of colon polyps, KRAS mutation, lymphatic invasion, new tumor after initial treatment, and residual tumor were risk factors; and pMMR and synchronous CRC present were protective factors in univariate regression." (PMID 34526059, 2021). "Recently, some researchers proposed that combination of KRAS mutation-based cancer vaccines and other immune therapy methods may evade immunosuppression and enhance the chance of a successful tumor treatment." (PMID 35198564, 2021). "KRAS is one of the most frequently mutated oncogenes in human cancer, occurring in 95% of pancreatic, 50% of colorectal, and 32% of lung adenocarcinomas, with descending prevalence in many other tumor types." (PMID 34680229, 2021). "For patients with locally advanced and/or metastatic PDAC, a G12D KRAS mutation within the primary tumor is an independent prognostic factor that results in significantly decreased overall survival, including those within the subgroup that receive chemotherapy." (PMID 34113570, 2021). "Genetic profiling of the tumor resections detected wild-type KRAS codon 12 and 13 mutations." (PMID 34688262, 2021). "CRISPR–Cas12a could identify the G12C mutation in five of 20 tumor tissues, while both PCR and direct sequencing discovered the KRAS mutation in three of the five tumor tissues." (PMID 33467412, 2021). "To expand upon their translational potential, we characterized the PDXs response to radiotherapy, demonstrated tumor growth inhibition with MEK inhibition in KRAS mutated PDXs and showed significant growth delay with the MET inhibitor savolitinib in a PDX harboring a MET exon 14 mutation." (PMID 33510214, 2021). "Moreover, calcium was found to inhibit proliferation and to induce apoptosis of tumor cells and reduce distinct patterns of mutation in proto-oncogene KRAS." (PMID 33922197, 2021). "Besides, the low frequency of resistance driver mutations found in this study is in good agreement with several analyses in primary CET SR tumor tissues reporting a low to moderate KRAS mutation frequency (9–21%)." (PMID 34271981, 2021). "KRAS mutations are associated with an immunosuppressive tumor microenvironment." (PMID 34073318, 2021). "PDAC is an aggressive tumor whose KRAS constitutive activation is the main hallmark for malignancy." (PMID 34638477, 2021). "Of 100 patients with isolated CRC‐LM, 57 (57%) had a KRAS or BRAF tumor tissue mutation." (PMID 33635598, 2021). "Studies have shown that KRAS mutations may lead to poor prognosis by enhancing tumor cell proliferation." (PMID 34957118, 2021).
tumor (continued). "KRAS mutations increase the glucose uptake in CRC cells via the upregulation of GLUT1 to generate more glycolytic intermediates for the utilization in different metabolic pathways in tumor expansion." (PMID 34887764, 2021). "Tumour biopsies were then genotyped for oncogenic KRAS mutations by ddPCR." (PMID 34203378, 2021). "Nonetheless, KRAS mutation is more common in CRC patients with early tumor recurrence." (PMID 33919924, 2021). "In addition to the overall differential methylation analysis, we also evaluated the effects of age, gender, tumor stage, location of the tumor (colon or rectum), and the mutation status (KRAS + vs. KRAS-) of the CRC samples." (PMID 34778269, 2021). "KRAS-mutated tumours have intrinsic resistance to EGFR TKIs, such as gefitinib or erlotinib." (PMID 32948832, 2021). "This heterogeneity of results may be due to the bias of inclusion criteria in several studies, where the KRAS mutation status of primary tumor is compared with a wide variety of metastatic sites." (PMID 33946899, 2021). "Additionally, we show that a novel preclinical oncofetal CS-targeting drug conjugate effectively eliminates NSCLC cells in vitro and inhibits KRAS-mutated NSCLC xenograft tumor growth in vivo." (PMID 34503301, 2021). "However, in a pilot study, out of the 9 evaluable patients that were vaccinated with a 21-mer peptide containing the corresponding KRAS mutation of the patient’s tumor, only 1 patient showed immune response." (PMID 33672917, 2021). "Moreover, patients with KRAS mutation had favorable clinical benefits of anti-PD-1/PD-L1 immunotherapy, and high PD-L1 expression in tumor cells was associated with improved overall survival in KRAS mutant patients." (PMID 33435990, 2021). "However, data on the effect of anti-EGFR treatment in patients with CRC with a KRAS A146 tumor mutation are conflicting." (PMID 34820593, 2021). "The recent discovery of covalent KRAS G12C inhibitors offers hope for improving the prognosis of NSCLC patients, but the development of combination therapies corresponding to tumor characteristics is still required given the vast heterogeneity of KRAS-mutated NSCLC." (PMID 34885068, 2021). "In addition, previous studies have highlighted the additional complex transcriptional and signaling network changes in KRAS-driven tumors co-mutated for the tumor suppressor LKB15." (PMID 33514834, 2021). "Post-treatment, MRI analysis showed decreased tumor size, while single cell transcriptomics concomitantly detected near complete ablation of the mutant-KRAS-associated subpopulation, signifying the presence of a pharmacologically targetable, tumor-associated subpopulation." (PMID 33854168, 2021). "This heterogeneity may be related to co-occurring genomic alterations, different KRAS mutations or tumor dependence/independence on KRAS, among others, that could condition intrinsic or acquired resistance to different treatments." (PMID 35083149, 2021). "The available tumor genotyping data showed mutation of KRAS for 16/43, mutation of NRAS for 3/29, NRAS unknown status for 14/43, mutation of BRAF for 5/35, and BRAF unknown status for 8/43." (PMID 33934494, 2021). "Therefore, colorectal tumors bearing KRAS mutations are associated with advanced disease status, poor tumor differentiation, distant metastasis and inferior survival in patients." (PMID 34742312, 2021). "During early events, KRAS, observed in 90% of PC tumours, is mutated at several hotspots." (PMID 34828525, 2021).
tumor (continued). "A recent study assessing the molecular profiles of NSCLC specimens revealed that tumors harboring KRAS G12C mutations exhibited a higher programmed death-ligand 1 (PD-L1) tumor proportion score and tumor mutational burden than those with KRAS non-G12C mutations." (PMID 34885068, 2021). "This exposure does not explain why a tumor of a tissue may have Ras isoforms with different mutant subtypes (e.g., a tumor with HRas favoring 61 codon mutations but KRas 12 codon mutations)." (PMID 34680208, 2021). "Analysis of clinically relevant mutations revealed an epidermal growth factor receptor (EGFR) mutation for the donor of LCSCs_a as well as tumor tissue of the donor of LCSCs_c showed mutations in the genes for the KRAS proto-oncogene (KRAS) and serine/threonine kinase 11 (STK11)." (PMID 33800955, 2021). "In addition to altered levels of particular cargo, exosomes secreted by cancer cells have been demonstrated to impact recipient cells by transporting mutated proteins with tumor promoting roles, such as KRAS." (PMID 34852849, 2021). "Furthermore, the analysis of plasma circulating tumor DNA (ctDNA) for KRAS mutations can help the real-time clinical management of patients when surgically resected tissues and re-biopsies are not available." (PMID 33467412, 2021). "In addition, with transcriptomic sequencing, the expression of many genes encoding oncogenic signaling proteins, including KRAS, was detected at the same levels in the bile and paired tumor tissues from patients with BTCs." (PMID 34572808, 2021). "We hypothesized that KRAS mutations, as a direct measurement of tumour biology, may be a powerful predictor of outcome also in patients with CRC with PM treated with perioperative modern chemotherapy." (PMID 34557315, 2021). "KRAS mutational status was mostly concordant between tumour tissues and liquid biopsy." (PMID 33953347, 2021). "Results: a total of 1117 patients were included; 38% had KRAS mutated tumours, 17% had G12C." (PMID 34503114, 2021). "Moreover, the expression of KRAS protein was associated with tumor stages and also occurred more frequently in ever-smokers (p = 0.002)." (PMID 33549031, 2021). "Furthermore, mutations of the KRAS gene in exon 2, codon 13 are associated with poor prognosis and a low survival rate, while mutations in exon 2 and codon 12 are associated with tumor progression and metastasis." (PMID 33919272, 2021). "However, among all genes analyzed, we found that KRAS is the top-ranked gene whose mutation status was significantly associated with predicted tumor sensitivity to trametinib for the largest number of tumor types (seven of the 31)." (PMID 33858332, 2021). "However, worse survival in patients with KRAS mutated tumours (as one group) compared to KRAS wt, as well as in patients with KRAS G12C compared to patients with KRAS non-G12C mutations, have also been reported." (PMID 34503114, 2021). "Analysis of genetic alterations by massive sequencing of primary tumor biopsies that were successfully engrafted identified the oncogenic KRAS mutation p.G12C in ADC samples LF05, LF09, and LF15, associating these mutations with successful PDX engraftment and aggressive disease." (PMID 34198671, 2021). "Therefore, we used the ddPCR method, which enables the qualitative and quantitative analysis of the presence and subtypes of KRAS mutations in tumor tissues and in cfDNA in blood." (PMID 34829828, 2021). "In terms of immune molecules, it was reported that those against the PD-1/PD-L1 checkpoint could improve the survival rates with KRAS-mutant NSCLC patients because KRAS mutations were correlated with tumor immunogenicity and an inflammatory TME." (PMID 34887858, 2021). "Interestingly, elimination of the wild type KRAS allele led to increased growth in soft agar, indicating tumor-suppressive characteristics of the wild type KRAS allele under these conditions." (PMID 34822010, 2021).
tumor (continued). "Furthermore, 94% patients harbor KRAS mutation in neoplasm, and prognosis of PDAC due to the extremely high mutant frequency failed to be predicted." (PMID 34733795, 2021). "Interestingly, this paracrine alteration of tumour metabolism is believed to occur in tandem with genetic mutations, such as mutations in KRAS which also acts to rewire PDAC metabolic pathways." (PMID 33445669, 2021). "In addition to the KRAS G12C mutation, mutations such as KRAS G12D also play an important role in the occurrence and development of tumours." (PMID 34012925, 2021). "BoC71 C3 tumor was chosen to test if a similar treatment-dependent alteration in the mutated KRAS allele frequency could be observed." (PMID 34271981, 2021). "Patients with mCRC with a KRAS A146 mutation represent a distinct molecular subgroup of patients with higher tumor burden and worse clinical outcomes, who might benefit from more intensive treatments." (PMID 34820593, 2021). "KRAS is the most commonly mutated isoform in various tumor types, followed by NRAS and HRAS." (PMID 34685488, 2021). "KRAS mutations induce the formation of a highly immunosuppressive tumor microenvironment." (PMID 34638488, 2021). "In addition, the mechanism of KRAS-mutation (G12D or G12V) affects the anti-tumor effects of fraxetin should be clarified." (PMID 34320467, 2021). "In search of chromatin-activated neoplasia effectors, the authors observed a rapid increase in alarmin cytokine IL-33 as well as a swift and selective gain of IL-33 locus in KRAS-mutated epithelial cells undergoing injury-facilitated chromatin switch in a BRD4-dependent manner." (PMID 34023857, 2021). "The remarkably therapeutic efficacy may be induced by increased virus replication as we have determined that MEKi treatment enhanced oHSV replication in BRAF wt/KRAS mutated tumor cells in vitro." (PMID 34578339, 2021). "Inactivation of a single MAPK or PI3K pathway has poor efficacy in KRAS-mutated tumours." (PMID 34012925, 2021). "The tumor of patient 1 revealed the previously detected KRAS p.G12R mutation (frequency: 4.6%), confirmed the NRAS p.Q61R mutation, previously detected using the corresponding antibody (frequency: 3.3%), and revealed an additional NRAS p.G12V mutation (frequency: 7.0%)." (PMID 34072863, 2021). "Tumor-specific mutations as KRAS could be detected by the usage of CTCs and could steer the treatment to the best possible multimodal regime for every single patient." (PMID 32235479, 2020). "The aim of this study was to evaluate the intertumoral heterogeneity of KRAS mutation status between the primary tumor and the corresponding metastasis or local recurrence in the similar cohort and to evaluate the ideal representative tissue for KRAS mutation testing." (PMID 33002027, 2020). "For example, patients 1, 3, and 6 all had KRAS missense mutations in all tumor sites tested." (PMID 31747139, 2020). "One intriguing possibility is that intracellular P. gingivalis may influence tumor development by synergizing with other oncogenic factors that upregulate the same pathways, such as mutant KRAS, the hallmark genetic mutation of PDAC." (PMID 32824786, 2020). "Moreover, sequencing data has allowed for better understanding of how secondary mutations synergize with oncogenic KRAS to drive tumor progression." (PMID 32550498, 2020). "Recent studies from independent groups have shed light on complex signaling pathways involved in the metabolic reprogramming in KRAS-transformed cells, which use macropinocytosis as the primary route for the uptake of large proteins, such as albumin, in a nutrient-deficient tumor microenvironment." (PMID 32807784, 2020).
tumor (continued). "Moreover, plasma KRAS mutations (30% of patients) were confirmed in tissue obtained from the primary tumor." (PMID 32629823, 2020). "Especially, KRAS mutations were found to occur in more than 90% of all tumor samples." (PMID 32545414, 2020). "In total, 19 patients showed a KRAS mutation (46.34%) in the primary tumor." (PMID 33002027, 2020). "Interestingly, all four KRAS-mutant tumours in the BW group had co-existent PI3K pathway mutations versus only 38% (10/26) of wt-KRAS cases (p = 0.0365)." (PMID 32520976, 2020). "Because of the high rate of KRAS mutation in PDAC tumours and pre-neoplastic lesions, a combination of the perfect sampling method and mutation detection technology should allow for a sensitivity approaching 90% for discrimination between PDAC and the healthy state." (PMID 32825312, 2020). "In addition, xenograft tumor models with the nude mouse using DLD1 cells with WT or mutated KRAS were established to examine the effects of AMPK activation on KRAS mutation-mediated anti-EGFR antibody resistance." (PMID 32703218, 2020). "However, the presence of ctDNA has been demonstrated by looking at tumor specific mutations in genes such as KRAS or tumor whole exome sequencing followed by mutation specific ddPCR in specific subgroups (high grade serous)." (PMID 34713045, 2020). "The objectives of this study were: 1) to compare EGFR and KRAS mutation status between plasma and tumor tissue in surgically resected TKI-naïve NSCLC; 2) to compare histopathological features between ctDNA shedding and non-shedding tumors; and 3) to evaluate parameters predicting ctDNA shedding." (PMID 32196518, 2020). "Since the tumor with either KRAS or BRAF mutation has a poor response to anti-EGFR therapy, any mucinous component (more than 5%) may be an adverse indicator for poor responsiveness to anti-EGFR therapy." (PMID 32384877, 2020). "Nevertheless, preclinical data as well as clinical data from other tumor entities bearing KRAS mutations give rise to hope for promising combination therapies involving targeted inhibition of the RAS signaling pathway, paving the way for suitable treatment options for patients suffering from PDAC." (PMID 32796566, 2020). "Tumor lesions with potential KRAS mutations were classified as mutant KRAS and wild type." (PMID 32079384, 2020). "However, presence of a Kirsten rat sarcoma (KRAS) mutation in the tumour confers resistance to this type of therapy." (PMID 32415199, 2020). "KRAS mutational status has been usually analyzed in tumor tissue, but obtaining biopsy specimens from pancreatic lesions may be difficult and requires invasive procedures, such as endoscopic ultrasound-guided fine needle aspiration (EUS-FNA)." (PMID 32630266, 2020). "Our data suggest that sampling either the primary (pre- or posttherapeutical tumor tissue) or metastatic lesion may be valid for the initial evaluation of KRAS mutation status predicting the response to anti-EGFR treatment and guiding clinical decisions." (PMID 33002027, 2020). "This aspect could determine an underestimation of the patients with co-occurring KRAS mutations, even though the low presence of ctDNA could be associated with lower tumor burden and better prognosis." (PMID 33520716, 2020). "In conclusion, these analyses suggest that p.A146 mutations merit full consideration when assessing patients’ tumor genetics and could also be considered for the development of further specific KRAS-inhibitors." (PMID 32079091, 2020). "In the dose escalation part, tumor samples were retrospectively analyzed for KRAS mutation." (PMID 32436621, 2020). "A KRAS mutation was found in the tumor in 34/48 (70.8%) adenocarcinoma patients." (PMID 33322500, 2020).